SMARCB1 (SWI/SNF related BAF chromatin remodeling complex subunit B1)
Diseases named in the same sentence as SMARCB1 in open-access papers (continued):
Sharing a sentence is not in itself a finding about the gene and the disease.
rhabdoid tumor (continued). "The germline variants of SMARCB1 have been documented in patients with one or more primary brain and/or kidney tumors, according to them having a predisposition to the development of rhabdoid tumors." (PMID 36295546, 2022). "A study in 35 cases of rhabdoid tumor (RT) patients identified that there was a very low mutational rate, with variants recurring only in SMARCB1 (SWI/SNF related, matrix-associated, actin-dependent regulator of chromatin, subfamily B, member 1), which appeared to contribute to the tumorigenesis." (PMID 36295546, 2022). "Interestingly, SMARCB1-deficient sinonasal carcinomas show a remarkable epigenetic similarity to adult sellar atypical teratoid/rhabdoid tumors, although they tended to aggregate slightly separate in t-SNE analysis." (PMID 36443295, 2022). "As an example, rhabdoid tumors are highly aggressive pediatric tumors genetically quiet except for germline or somatic mutations of SMARCB1, a member of the SWI–SNF chromatin remodeling complex, functioning as a tumor suppressor in a broad range of developing tissues." (PMID 34327198, 2021). "Rhabdoid tumors are pediatric cancers driven by loss of SMARCB1/INI1." (PMID 34299136, 2021). "Malignant rhabdoid tumors (MRT), also known as extra-renal rhabdoid tumors or rhabdoid tumors of the soft-tissues, are aggressive pediatric cancers characterized by loss of the tumor suppressor SWI/SNF-related matrix-associated actin-dependent regulator of chromatin subfamily B member 1 (SMARCB1)." (PMID 34204560, 2021). "In addition, ~90% of malignant rhabdoid tumors (MRT) harbor SNF5/SMARCB1 (integrase interactor 1/SWI/SNF‐related matrix‐associated actin‐dependent regulator of chromatin subfamily B member 1) mutations." (PMID 33419967, 2021). "Furthermore, recent next-generation sequencing studies demonstrate an overlap between SMARCB1-dependent promoter targets and tissue-specific lineage-determining genes that are downregulated in SMARCB1-deficient malignant rhabdoid tumours." (PMID 34680294, 2021). "Importantly, these pathways have been linked to aberrant SMARCB1‐deficient SWI/SNF activity in rhabdoid tumor." (PMID 33332735, 2021). "In addition, BRD9 is a specific vulnerability in SMARCB1-deficient malignant rhabdoid tumours and in synovial sarcoma (SS18-SSX) cells." (PMID 33941852, 2021). "This holds true in particular for pediatric tumors which, due to different etiology and tissue origin, usually are characterized by a remarkably low number of somatic mutations, the best example of which includes rhabdoid tumor displaying solely SMARCB1 recurrent mutations." (PMID 34281526, 2021). "In addition, loss of SMARCB1 is the defining genetic change in both synovial sarcoma and malignant rhabdoid tumors (MRTs)." (PMID 32629987, 2020). "Increased sensitivity to BTZ in renal medullary carcinoma and other SMARCB1-deficient cells, including MRTs (Malignant rhabdoid tumors) and ATRTs, might be dependent on the loss of SMARCB1." (PMID 32235770, 2020). "However, loss of SMARCB1 is reported in various cancers including malignant rhabdoid tumors, epithelioid sarcoma, medullary carcinoma, synovial sarcoma, familial schwannomatosis, extraskeletal myxoid chondrosarcoma, and small-cell hepatoblastoma." (PMID 32629987, 2020). "The SWI/SNF mating-type switching (SWI) and sucrose nonfermenting (SNF) subfamily has specifically been investigated in malignant rhabdoid tumors, pediatric and highly lethal neoplasms of the kidney and brain where SMARCB1 (INI-1) is frequently mutated either at germline or at somatic level." (PMID 31455041, 2019). "The mechanisms by which SMARCB1 germline mutations predispose to rhabdoid tumors versus schwannomas are still unknown." (PMID 28824165, 2017). "SMARCB1 mutations predispose to rhabdoid tumors and schwannomas but the mechanisms underlying the tumor type specificity are unknown." (PMID 28824165, 2017).
rhabdoid tumor (continued). "Smarcb1 loss in early neural crest was necessary to initiate tumorigenesis in the cranial nerves and meninges with typical histological features and molecular profiles of human rhabdoid tumors." (PMID 28824165, 2017). "SNF5 (SMARCB1 or BAF47) is mutated in 100 % of malignant rhabdoid tumors." (PMID 27188282, 2016). "A recent study in SMARCB1, a potent tumor suppressor with loss of expression, especially in certain rhabdoid tumor types and which is a core subunit of the SWI/SNF complex, showed persistent activation of AKT in SMARCB1-deficient tumor cells, contributing to survival and proliferation." (PMID 24036443, 2013). "In rhabdoid tumors loss of SMARCB1 activates those programs." (PMID 23764045, 2013). "In rhabdoid tumors the situation might be somewhat different as biallelic mutation of the chromatin remodeling factor SMARCB1 deregulates multiple tumor pathways (SHH, polycomb mediated pathways and Rb mediated pathways)." (PMID 23764045, 2013). "As HDAC inhibition has been shown to restore imprinted tumor suppressors such as CDKN1C in rhabdoid tumors, we hypothesized that HDACi might generally compensate the missing chromatin remodeling function caused by SMARCB1 loss." (PMID 23764045, 2013). "However there have been several reports of germ-line mutations in SMARCB1 in association with rhabdoid tumor and with other tumors including epitheloid sarcoma and familial schwannomatosis." (PMID 20003390, 2009). "Most histopathology laboratories confirm the diagnosis of rhabdoid tumor based on loss of immunostaining for SMARCB1 protein in the tumor cell nuclei and this correlates well with the presence of inactivating SMARCB1 mutations and with homozygous deletion of the gene." (PMID 20003390, 2009). "Moreover, SMARCB1 mutations in the germline may predispose individuals to both malignant rhabdoid tumours and schwannomatosis, a rare genetic disorder that results in multiple tumours called schwannomas, but they seldom occur simultaneously in the same family." (PMID 39471843, 2024). "In addition, up to 20% of malignant rhabdoid tumors have germline SMARCB1 deletions or mutations." (PMID 38355560, 2024). "For instance, atypical deletions could involve the tumor suppressor gene SMARCB1 (MIM_609322), which is associated with rhabdoid tumors, or DGCR8 gene (MIM_609030), which has been found to result in aberrant levels of miRNA leading to an increased susceptibility to malignancies." (PMID 37635986, 2023). "In addition to the SMARCB1 events, we identified other whole-chromosome events and single-nucleotide variants in tumors, but none were found to be prognostic, diagnostic, or offer therapeutic potential for rhabdoid tumors." (PMID 35912263, 2022). "Herein we sought to establish, by reverse modeling of SMARCB1 loss through the re-introduction of SMARCB1 into malignant rhabdoid tumors cell lines representative of MRTK (G401) and ATRT (BT16), just how dysregulation of the chromatin landscape could contribute to oncogenesis." (PMID 34071089, 2021). "Although rarely, it can also result from the constitutional ring chromosome 22 (r22): during mitosis the ring chromosome may lead to an increased rate of somatic mutations, resulting in rhabdoid tumor predispositions when the tumor-suppressor gene SMARCB1 is involved." (PMID 34777208, 2021). "Similarly, in malignant rhabdoid tumours, SMARCB1 loss reduces the ability to bind to typical enhancers, but not to super-enhancer sites, indicating that the residual SWI/SNF subunits are sufficient for tumour progression and survival through formation of ncBAF complexes." (PMID 33941852, 2021). "Moreover, mutation in SMARCB1 are typically found in rhabdoid tumors and epithelioid sarcomas." (PMID 31470906, 2019).
rhabdoid tumor (continued). "Thus atypical teratoid/rhabdoid tumors (central nervous system rhabdoid tumors) and renal and extrarenal rhabdoid tumors seem to be genetically related and SMARCB1 loss detection can thus play an integral part in differentiating rhabdoid tumors from other tumors with similar histologic features." (PMID 26064731, 2015). "Even though rhabdoid tumors are aggressive tumors, they present a simple genetic configuration with lack of chromosomal instability and a mutation rate among the lowest in all sequenced cancer genomes with loss of SMARCB1 as the only consistently recurrent event." (PMID 26064731, 2015). "In rhabdoid tumors, SMARCB1 re-expression increased SWI/SNF occupancy at distal sites generally but not at SE sites, where it remained unchanged." (PMID 39906560, 2025). "Dual inhibition of EZH1/2 is also one of the promising therapeutic approaches for SMARCB1-deficient tumors worth exploring in future clinical practice.EZH1 and EZH2 contribute to the growth of MRT (Malignant Rhabdoid Tumor) cells and H3K27 methylation." (PMID 40115023, 2025). "For example, loss of SMARCB1 and inhibition of EZH2 cause synthetic lethality in malignant rhabdoid tumor (MRT) cells." (PMID 40599851, 2025). "For example, somatic mutation-based biallelic inactivation of SMARCB1, a core component of the SWI/SNF complex, is frequently observed in Atypical Teratoid/Rhabdoid Tumor (AT/RT) (approximately 98%)." (PMID 40599851, 2025). "Once the DNA methylation analysis on the rhabdoid tumor sample revealed a high-confidence match to ATRT and loss of SMARCB1, the diagnosis of ATRT was confirmed with loss of INI-1 expression in the rhabdoid tumor component." (PMID 41155355, 2025). "Although malignant rhabdoid tumours are uncommon in patients with SMARCB1-related SWN, malignant peripheral nerve sheath tumours (MPNSTs) have been reported to occur in these patients." (PMID 40794298, 2025). "Subsequently, SMARCB1 was found to act as a bona fide tumour suppressor in malignant rhabdoid tumours (MRTs) and many other tumour types." (PMID 40794298, 2025). "Familial cases involving both atypical teratoid/rhabdoid tumor (AT/RT) and renal rhabdoid tumor due to the same INI1 (SMARCB1) gene alteration have also been reported, further supporting the role of genetic background in tumor predisposition syndromes." (PMID 40718162, 2025). "In high-grade uRCCs, particularly in young patients or those with sickle cell trait, INI1 (SMARCB1) staining is critical to identify renal medullary carcinoma or related rhabdoid tumors." (PMID 41426798, 2025). "Malignant rhabdoid tumours are genetically defined by inactivation of the SMARCB1 gene in almost all cases." (PMID 40983796, 2025). "We demonstrate that re-expression of SMARCB1 increases rhabdoid tumor cells’ viability in the presence of a range of concentrations of HHT (red lines), while expression of GFP does not (black lines)." (PMID 39542244, 2024). "SMARCB1, a subunit of the SWI/SNF chromatin remodeling complex, is the causative gene of rhabdoid tumors and epithelioid sarcomas." (PMID 38839769, 2024). "N-MYC amplification was found in two of the twelve neuroblastomas and SMARCB1 amplification in two of the five malignant rhabdoid tumors." (PMID 38254862, 2024). "Loss of SMARCB1 serves as a hallmark of atypical teratoid/rhabdoid tumors (AR/TT), a rare brain tumor occurring in young children with the deletion of SMARCB1/INI-1." (PMID 39233954, 2024). "To strengthen our findings, we re-analyzed published RNA-seq data in a rhabdoid tumors cell line (I2A) with inducible SMARCB1 re-expression." (PMID 39472584, 2024). "Almost all rhabdoid tumors and epithelioid sarcomas are deficient in SMARCB1 (SWI/SNF-related, matrix-associated actin-dependent regulator of chromatin, subfamily B, member 1), a subunit of the SWI/SNF chromatin remodeling complex." (PMID 38839769, 2024).
rhabdoid tumor (continued). "To characterize how BRG1 participates in chromatin remodeling and gene expression in SMARCB1-deficient cells, we performed a genome-wide characterization of the impact of BRG1 depletion in multiple rhabdoid tumor cell lines." (PMID 38473277, 2024). "EZH2 inhibitors induced differentiation and apoptosis in SMARCB1-deleted malignant rhabdoid tumor xenograft." (PMID 38472198, 2024). "Eleven patients were re-classified as having rhabdoid tumors on CHIC retrospective consensus review (including one patient previously confirmed by author MF), with confirmed loss of SMARCB1 expression by INI1 immunohistochemistry in 10 of the patients." (PMID 36672416, 2023). "Conversely, while nearly all cases of extracranial rhabdoid tumors harbored mutations of SMARCB1, SMARCA4 mutations were only observed in approximately 0.5%–2% atypical teratoid/rhabdoid tumors." (PMID 38124509, 2023). "This antagonistic relationship between PRC and SWI/SNF is well illustrated for the SMARCB1 deficient malignant rhabdoid tumour, and EZH2 inhibitors led to regression of malignant rhabdoid tumours in vitro and in vivo." (PMID 38275587, 2023). "The loss of the chromatin remodeling gene SMARCB1 (INI1) due to inactivating mutation and/or deletion is characteristic of malignant rhabdoid tumors arising in childhood." (PMID 37239344, 2023). "Indeed, patients #10, 12, and 21 suffered from a rhabdoid tumor predisposition syndrome 1 (RTPS1) due to pathogenic SMARCB1 germline variants that may have caused multiple independent tumor lesions, but the five other cases with RTPS1 did not demonstrate multiple independent tumors." (PMID 37450044, 2023). "Agents targeting EZH2 have shown to induce tumor regression and promote radiation sensitivity in models of SMARCB1/INI1-deficient tumors, including poorly differentiated chordomas, malignant rhabdoid tumors and epithelioid sarcomas." (PMID 37456229, 2023). "To test this at the level of gene expression, we used the mSigDB cell-type-specific signature collection (C8), supplemented with a signature that we derived from SMARCB1 re-introduction experiments in rhabdoid tumor cell lines." (PMID 37554444, 2023). "Eleven patients were identified as having rhabdoid tumors/loss of SMARCB1 expression by CHIC consensus review, including 10 with documented loss of SMARCB1 expression." (PMID 36672416, 2023). "Molecular characterization of SCU HBs revealed that a proportion of HBs with SCU histology are actually primary rhabdoid tumors with characteristic loss-of-function variants or deletions of the SMARCB1 gene, loss of INI1, low AFP levels, and poor outcomes." (PMID 36672416, 2023). "Ongoing and future large, controlled studies including central consensus review, AFP at diagnosis for every patient, and INI1 immunohistochemistry or SMARCB1 genetic testing for suspected rhabdoid tumor cases would be required to confirm these findings." (PMID 36672416, 2023). "The association of chromatin remodelers with diseases was first found in 1999, when the subunit SNF5 (SMARCB1) of the SWI/SNF remodeling complex was discovered to be inactivated in rhabdoid tumors." (PMID 37175555, 2023). "Complete loss of SMARCB1 was initially identified in difficult-to-treat pediatric tumors such as malignant rhabdoid tumors (MRT) and atypical teratoid/rhabdoid tumors (AT/RT)." (PMID 35806102, 2022). "Inhibition of EZH2 activity induced cell death in malignant rhabdoid tumor (MRT, SMARCB1-deficient cancer) cell line." (PMID 35806102, 2022). "In fact, recent studies have proposed that rhabdoid tumors arise from a small population of neural crest cells that lose SMARCB1 during development." (PMID 35892904, 2022). "Further study is needed to determine the clinical efficacy of nuclear export inhibition in C-terminal truncated SMARCB1 rhabdoid tumors." (PMID 35892904, 2022). "The prototypical example is inactivation of SMARCB1 (INI1) in pediatric malignant rhabdoid tumors (MRTs) and epithelioid sarcomas." (PMID 35864317, 2022).
rhabdoid tumor (continued). "The role of this complex in embryonal tumors is clearly exemplified in malignant rhabdoid tumors (MRT), which are characterized by the complete loss of SWI/SNF subunit SMARCB1 (95% of cases) or SMARCA4 (5% of cases)." (PMID 33718380, 2021). "In mouse experiment, early embryonic SMARCB1 inactivation between E6 and E10 induced rhabdoid tumors that closely resembled all transcriptional subclasses of human tumors." (PMID 34327198, 2021). "Rhabdoid tumor is a pediatric cancer that is most commonly characterized by biallelic deletion in SMARCB1 of the SWI/SNF chromatin remodeling complex." (PMID 33332735, 2021). "Several other SMARCB1 mutant cancers, including malignant rhabdoid tumors (MRT) and atypical teratoid rhabdoid tumors (ATRT) are candidates for treatment with EZH2 inhibitors." (PMID 34202528, 2021). "This was first appreciated when recurrent inactivation of SMARCB1 (also known as INI-1 and BAF47, and encoded by SMARCB1), were discovered in malignant rhabdoid tumor, an aggressive sarcoma of childhood." (PMID 33921435, 2021). "Rhabdoid tumor (RT) is a pediatric cancer characterized by the inactivation of SMARCB1, a subunit of the SWI/SNF chromatin remodeling complex." (PMID 33332735, 2021). "Rhabdoid tumor (RT) is emblematic of this dysregulated complex and driven by biallelic inactivation of specific subunits, SMARCB1, or less commonly SMARCA4." (PMID 33332735, 2021). "In order to link mithramycin‐mediated eviction of SWI/SNF binding and accumulation of H3K27me3 to the described cellular hypersensitivity of rhabdoid tumor, we next examined the importance of SMARCB1 deletion to these effects." (PMID 33332735, 2021). "The genetic background of rhabdoid tumors and a significantly higher responding rate suggest that SMARCB1-mutant tumors can be therapeutically targeted by ICB therapy." (PMID 33419967, 2021). "Inactivation of SMARCB1 has been described as a critical event in various tumors, including malignant rhabdoid tumors and epithelioid sarcoma." (PMID 34070849, 2021). "It is notable, the peaks in BMP1 as well as multiple other genes overlapped with published ATAC‐seq peaks that were gained following SMARCB1 complementation in rhabdoid tumor cells (Fig EV4)." (PMID 33332735, 2021). "The SMARCB1/INI1 gene was identified as a potent tumor suppressor in rhabdoid tumors, epithelioid sarcomas, schwannomatosis, synovial sarcomas, and other conditions." (PMID 32064045, 2020). "Extrarenal rhabdoid tumors show polygonal rhabdoid cells with abundant eosinophilic cytoplasm and are positive for cytokeratin and EMA, with loss of SMARCB1 (INI1) expression." (PMID 32867125, 2020). "In malignant rhabdoid tumors, which are highly aggressive pediatric cancers, loss of the SWI-SNF core subunit SNF5 (also known as SMARCB1) results in unopposed EZH2 activity." (PMID 33003334, 2020). "SMARCB1 has been known to regulate the cell cycle through P21 in malignant rhabdoid tumors (MRT), which are the prototypical SMARCB1-deficient tumors." (PMID 32492816, 2020). "All rhabdoid tumors with homozygous mutations and/or deletions of SMARCB1 show loss of nuclear expression of INI1/BAF47 protein, that can be detected by immunohistochemistry." (PMID 31835848, 2019). "Here, using a genome-wide CRISPR-Cas9 screen, we show that BRD9 is a specific vulnerability in pediatric malignant rhabdoid tumors (RTs), which are driven by inactivation of the SMARCB1 subunit of SWI/SNF." (PMID 31015438, 2019). "Previous trials have explored the use of aurora A kinase inhibition in malignant rhabdoid tumors, with an attempt to augment radiation sensitivity in cell lines that overexpress AAK, which occurs in cells with mutations in SMARCB1." (PMID 31835848, 2019). "In light of molecular studies showing SMARCB1 deletion in these tumors, it is now recognized that most small cell, undifferentiated liver tumors represent an aggressive unrelated tumor—the malignant rhabdoid tumor (MRT)." (PMID 31835848, 2019).